FAM151B (family with sequence similarity 151 member B)
Description:
Essential for survival of retinal photoreceptor cells.
Synonyms: UNQ9217
Tractability: No criterion of Open Targets' tractability assessment is met for any kind of drug.
Gene: Protein-coding gene on chromosome 5 (80,487,969 to 80,542,563, forward strand). Ensembl gene ENSG00000152380.
Subcellular location (Human Protein Atlas): Cytosol
Gene Ontology:
Molecular function: protein binding
Biological process: photoreceptor cell development
Genetic constraint (gnomAD): Loss-of-function variants: 18 observed, 24.85 expected, observed/expected ratio (o/e) 0.72, 90% interval 0.5 to 1.07. The upper end of that interval is the gene's LOEUF score, 1.07, which puts it in group 4 of 6, group 1 being the genes least tolerant of losing a copy. Missense variants: 249 observed, 292.35 expected, observed/expected ratio (o/e) 0.85, 90% interval 0.77 to 0.95. Synonymous variants: 92 observed, 101.31 expected, observed/expected ratio (o/e) 0.91, 90% interval 0.77 to 1.08.
Homologues: Orthologues: chimpanzee FAM151B (99% identical), macaque FAM151B (97% identical), dog FAM151B (92% identical), mouse Fam151b (85% identical), pig FAM151B (84% identical), rat Fam151b (84% identical), rabbit FAM151B (76% identical), guinea pig FAM151B (75% identical), tropical clawed frog fam151b (58% identical), zebrafish fam151b (52% identical), Drosophila melanogaster CG7231 (35% identical), Caenorhabditis elegans mnr-1 (27% identical). Paralogues in human: FAM151A (44% identical).
Diseases named in the same sentence as FAM151B in open-access papers:
FAM151B is named in the same sentence as 3 diseases in open-access papers, as found by Europe PMC text mining. Sharing a sentence is not in itself a finding about the gene and the disease. The quoted sentences say what the papers report.
retinal disease (1 paper, 2020). "Clear loss of function mutation in FAM151B are on the whole rare, and show a pattern similar to other retinal disease-causing genes." (PMID 31949211, 2020).
FAM151B also shares sentences with these, for which no sentence is quoted: retinal degeneration (1 paper); tumor (1).